DOT1L (DOT1 like histone lysine methyltransferase)
Description:
Histone methyltransferase that methylates 'Lys-79' of histone H3. Histones in nucleosomes are preferred as substrate compared to free histones. Binds to DNA. Together with MLLT3/AF9, is involved in SCNN1A transcriptional repression following H3K79 hypermethylation at the promoter (By similarity).
Synonyms: KIAA1814; KMT4; DOT1; NDNS
Tractability: Small molecule: a structure with a bound ligand is known; a high-quality ligand is known; it has a high-quality binding pocket; it belongs to a druggable protein family. PROTAC: ubiquitination databases record sites on it; a small molecule that binds it is known.
Target class: Writer; Protein methyltransferase; Epigenetic regulator
Chemical probes: CHEMBL2171169, EPZ-5676 (high quality), EPZ004777 (high quality), PD081283, PD082588, PD082793, PD085115, SGC0946 (high quality)
Gene: Protein-coding gene on chromosome 19 (2,163,933 to 2,232,578, forward strand). Ensembl gene ENSG00000104885.
Subcellular location: Nucleus; Cytoplasm
Subcellular location (Human Protein Atlas): Nucleoplasm
Pathways (Reactome):
Chromatin organization: PKMTs methylate histone lysines
Gene Ontology:
Molecular function: DNA binding; histone H3K79 methyltransferase activity; histone H3K79 trimethyltransferase activity; histone methyltransferase activity; nucleic acid binding; protein binding; histone H3 methyltransferase activity
Biological process: positive regulation of transcription by RNA polymerase II; regulation of receptor signaling pathway via JAK-STAT; regulation of transcription regulatory region DNA binding; DNA damage checkpoint signaling; DNA repair; subtelomeric heterochromatin formation; telomere organization; heterochromatin formation; negative regulation of gene expression, epigenetic; regulation of cell cycle; regulation of gene expression
Cellular component: nucleoplasm; nucleus; protein-containing complex; chromosome, telomeric region; cytoplasm
Genetic constraint (gnomAD): Loss-of-function variants: 33 observed, 137.45 expected, observed/expected ratio (o/e) 0.24, 90% interval 0.18 to 0.32. The synonymous counts are far from expectation, so gnomAD's model fits this gene poorly and the ratio says little. Missense variants: 1,847 observed, 2,016.5 expected, observed/expected ratio (o/e) 0.92, 90% interval 0.88 to 0.95. Synonymous variants: 1,135 observed, 926.79 expected, observed/expected ratio (o/e) 1.22, 90% interval 1.17 to 1.29.
Homologues: Orthologues: chimpanzee DOT1L (99% identical), macaque DOT1L (96% identical), dog DOT1L (85% identical), mouse Dot1l (84% identical), rat Dot1l (84% identical), pig DOT1L (84% identical), guinea pig DOT1L (72% identical), tropical clawed frog dot1l (60% identical), zebrafish dot1l (47% identical), Drosophila melanogaster gpp (29% identical), Caenorhabditis elegans dot-1.1 (15% identical), Caenorhabditis elegans dot-1.4 (7% identical), and 4 more.
Diseases named in the same sentence as DOT1L in open-access papers:
DOT1L is named in the same sentence as 126 diseases in open-access papers, as found by Europe PMC text mining. Sharing a sentence is not in itself a finding about the gene and the disease. The quoted sentences say what the papers report.
leukemia (201 papers, 2010 to 2026). A malignant (clonal) hematologic disorder, involving hematopoietic stem cells and characterized by the presence of primitive or atypical myeloid or lymphoid cells in the bone marrow and the blood. "DOT1L has been implicated as an oncogene for MLL-rearranged leukemia, a finding that sparked the development of DOT1L inhibitors." (PMID 39765675, 2024). "In particular, DOT1L has a well-documented role in MLL-fusion leukemia with aberrant rearrangement of MLL1 alleles." (PMID 39394462, 2024). "In MLL-r leukemia, the histone methyltransferase DOT1L has been shown to be associated with the MLL fusion protein complex, and DOT1L is required for leukemogenesis in different cellular and organismal model systems." (PMID 37720104, 2023). "For example, in MLL-rearranged leukemia DOT1L inhibition is used for treatment, whereas DOT1L ablation has also been associated with therapy resistance of mouse melanoma." (PMID 36425063, 2022). "In summary, we present a general overview of DOT1L as a target in MLL-rearranged leukemias to provide valuable guidance for DOT1L-associated drug development in the future." (PMID 35331314, 2022). "DOT1L inhibitors are being investigated in clinical trials for treatment of leukemia caused by rearrangement of the MLL gene (Mixed-Lineage Leukemia-rearranged)." (PMID 36425063, 2022). "To dissect the underlying mechanisms of the induced anti-leukemia effect and confirm the disruption of DOT1L recruitment to MLL target gene loci Hoxa9 and Meis1, we performed a chromatin immunoprecipitation coupled with qPCR (ChIP-qPCR)." (PMID 33562706, 2021). "Although both factors regulate PIM1 expression, the FLT3-ITD axis is more sensitive and is responsible for PIM1 downregulation with low-dose DOT1L inhibitor treatment in MLL-r leukemia also bearing the FLT3-ITD mutation." (PMID 34263728, 2021). "Leukemias harboring MLL-rearrangements are uniquely susceptible to DOT1L inhibition and MV4;11, a biphenotypic leukemia cell line harboring an MLL-AF4 translocation, is one of the most sensitive." (PMID 34263728, 2021). "DOT1L has additionally been implicated in oncogenesis for multiple leukemias, including mixed lineage leukemia (MLL), acute lymphoblastic leukemia (ALL), and acute myeloid leukemia (AML)." (PMID 30881380, 2019). "The mislocalisation of DOT1L activity is strongly associated with leukaemias resulting from oncogenic chromosomal translocations involving the MLL gene." (PMID 29495487, 2018). "Aberrant transcriptional activation via H3K79 methylation by DOT1L has been implicated in the development of leukemias that derive from oncogenic chromosomal rearrangements of the MLL (mixed lineage leukemia) gene." (PMID 29495487, 2018). "In consequence, SETD2 loss led to hyper-sensitization of MLL-leukemia cells to small-molecule-mediated DOT1L inhibition, which provides a rationale for potential future combination therapies in AML." (PMID 29777171, 2018). "Collectively, these findings suggest that DOT1L KMT domain-focused indel mutagenesis had produced a novel allele that renders leukemia cells resistant to EPZ-5676-mediated growth arrest." (PMID 28231254, 2017). "DOT1L, the sole methyltransferase for three states of H3K79me, is implicated in leukemia, co-lorectal cancer, and dilated cardiomyopathy." (PMID 29796335, 2017). "Human DOT1L is important in a subset of leukemias that express an MLL fusion protein caused by rearrangements of the MLL gene (MLL-r)." (PMID 27922451, 2016). "For example, transcription factors Dot1l and Nrip1 which are part of the ‘early-maintained’ response have been implicated in mixed lineage leukaemia and acute lympoblastic leukaemia respectively." (PMID 26415229, 2015). "MLL-associated leukemia are aggressive, characterized by a frustrating therapy outcome, and are DOT1L-dependent." (PMID 24497836, 2014). "Aberrant methylation of H3K79 by DOT1L is associated with MLL rearrangements in leukemia, possibly by mistargeting of DOT1L activity." (PMID 23754963, 2013).
leukemia (continued). "These leukemia-associated fusion proteins recruit DOT1L to target genes, with a concomitant increase in H3K79 methylation around the targeted site, upregulation of gene expression, and subsequent development of leukemia." (PMID 21291527, 2011). "Using proteomics, we identified the leukemia-associated Mllt10/Af10 and the methyltransferase Dot1l as Tcf4/β-catenin interactors in mouse small intestinal crypts." (PMID 21103407, 2010). "The leukemia-associated Mllt10/Af10 and its partner the histone methyltransferase Dot1l are identified as Tcf4/β-catenin co-activators and shown to be essential for Wnt-driven endogenous gene expression, intestinal development and homeostasis." (PMID 21103407, 2010). "In this study, using a proteomics approach, we identify the leukemia-associated Mllt10/Af10 and its partner the histone methyltransferase Dot1l as interactors with Tcf4/β-catenin in the mouse small intestinal epithelium." (PMID 21103407, 2010). "However, in leukemic cells, sustained expression of these genes due to aberrant DOT1L activity contributes to the blockage of cellular differentiation and the promotion of unchecked cellular proliferation, hallmark features of leukemia." (PMID 40374809, 2025). "Therefore, disruption of the PPIs between AF9/ENL and AF4/AFF4 or DOT1L is a potentially useful therapy for MLL-r leukemia by suppressing SEC-mediated gene expression and DOT1L-caused H3K79 methylation." (PMID 37958457, 2023). "In this study we report that targeting MEN1 gene-encoded protein menin, known as an important DOT1L cofactor in MLL-rearranged leukaemia and antiestrogen therapy-resistant breast cancer cells may represent an effective therapeutic approach against OC." (PMID 36333801, 2022). "Similarly, leukemias bearing AF10 gene fusions require DOT1L for leukemia initiation and maintenance, and DOT1L loss leads to decreased expression of downstream fusion targets." (PMID 35712672, 2022). "In addition to DOT1L’s methyltransferase activity, studies have shown that loss of Dot1 complex (DotCom, composed of AF9, AF10, ENL and AF17) components AF10, and ENL have a similar effect on leukemia cells as loss of DOT1L." (PMID 35712672, 2022). "Preclinical studies demonstrated that the addition of pinometostat to conventional chemotherapy might sensitize MLL-associated leukemia cells to chemotherapy, by way of DOT1L inhibition." (PMID 35740427, 2022). "The loss/degradation of DOT1L has also been proposed for MLL-rearranged leukemias." (PMID 35331314, 2022). "Studies of methyltransferase mutant, AF9-binding disrupted mutant, and wild type DOT1L models in vivo showed loss of DOT1L-AF9 was sufficient to inhibit leukemia cell growth and increase their differentiation to similar levels observed with DOT1L enzyme-dead mutant." (PMID 35712672, 2022). "Indeed, we observed a significant decrease in Meis1 and Hoxa9 expression in Δ10-DOT1L and I867A-DOT1L leukemia cells, comparable to the changes induced by complete loss of DOT1L (empty vector) or by DOT1L enzymatic inhibition (RCR-DOT1L)." (PMID 33562706, 2021). "H3K79 methylation is catalyzed by DOT1L, which is implicated in both solid cancer and leukemia." (PMID 35201498, 2021). "Other studies have shown that higher levels of H3K79me2 are associated with poorer prognosis in MLL-r leukemias, and the fusion of DOT1L and MLL partners, AF4, AF9, ENL, and AF10, leads to misregulation of DOT1L targets, resulting in aberrant H3K79me2 activity followed by leukemic transformation." (PMID 29665865, 2018). "Interestingly, more recent studies suggest that H3K79met patterns are more consistently associated with MLL1-rearranged leukemia than H3K4met profiles, and DOT1L is essential for MLL1-driven leukemogenesis as a member of MLL1-associated multiprotein complexes." (PMID 28054944, 2017). "DOT1L has emerged as an anticancer target for MLL-associated leukaemias; however, itsfunctional role in solid tumours is largely unknown." (PMID 26199140, 2015).
leukemia (continued). "However, enzymatically dead versions of DOT1L are unable to rescue DOT1L deficiencies in MLL-FP leukemias and DOT1L enzymatic inhibitors have little effect on other leukemias, suggesting that whatever the specific role is, H3K79Me2 is key for maintaining the expression of MLL-FP target genes." (PMID 24213472, 2012). "Together, our findings establish DOT1L as a component of transcriptional memory co-opted in leukaemia and suggest it serves as the missing link balancing the opposing forces of the MLL-Polycomb axis." (PMID 41634341, 2026). "KMT2A‐rearranged leukemia cells on the other hand are highly addicted to DOT1L for the maintenece of oncogenic gene expression." (PMID 39887730, 2026). "EPZ004777 has been identified as a potent inhibitor of DOT1L and has been shown to inhibit leukemogenic gene expression, particularly in cells carrying Mixed Lineage Leukemia translocations, by blocking H3K79 methylation in in vivo studies." (PMID 40136427, 2025). "In KMT2A-rearranged leukemia the enzymatic activity of DOT1L appears to be relevant and inhibition shows therapeutic efficacy in preclinical model systems and modest activity in a phase-1 clinical trial." (PMID 40781484, 2025). "For example, the dependency of MLL-rearranged leukemias on DOT1L and on Menin has led to trials of inhibitors against these epigenetic co-factors." (PMID 40651916, 2025). "The PPI of AF9 with DOT1L recruits DOT1L to AF9 targeted genes increasing their methylation therefore increasing their expression leading to leukaemia." (PMID 39817557, 2025). "In gene set enrichment analysis (GSEA) DOT1L-ko HEL cells had lost leukemia stem cell (LSC) features, MYC-targets and the expression of KMT2A target genes." (PMID 40781484, 2025). "Studies conducted in cell culture and mouse xenograft disease models have demonstrated that DOT1L inhibition via EPZ004777 provides a strong molecular basis for the development of targeted therapeutic approaches against MLL-rearranged leukemias." (PMID 40136427, 2025). "The stabilised CBP acetylates DOT1L(K358) to protect it from proteasomal degradation, mediating the high level of H3K79me2 for the upregulated expression of leukaemia genes in MLLr-AML." (PMID 38671157, 2024). "LAMP5-AS1 was found to regulate the self-renewal program and differentiation block by enhancing the methyltransferase activity of DOT1L in MLL leukemia." (PMID 38374003, 2024). "This view is supported by our findings that CBP deficiency blocks cell growth and increases proteasomal degradation of the DOT1L protein in MLLr leukaemia." (PMID 38671157, 2024). "Our study has revealed that CREB binding protein (CBP) is a linker between ATM and DOT1L that sustains MLLr leukaemia." (PMID 38671157, 2024). "Inhibition of both menin and DOT1L is necessary to evict MLL-AF9 from chromatin at key tumor-promoting genes in MLL-AF9-driven leukemia cells." (PMID 39336822, 2024). "DotComs have been extensively studied as therapeutic targets in the context of MLL; where DOT1L activity is augmented to facilitate leukaemia gene expression, a role for DotComs in immune cell regulation has not been explored." (PMID 38962004, 2024). "Preclinical studies have demonstrated that combining DOT1L inhibitors with menin inhibitors significantly enhances anti-leukemic effects in KMT2Ar leukemias." (PMID 39682203, 2024). "In KMT2Ar leukemias, DOT1L plays a vital role in sustaining the oncogenic transcriptional programs driven by KMT2A-fusion proteins." (PMID 39682203, 2024). "For instance, hypermethylation of H3K79 by DOT1L is crucial for the onset of MLL‐rearranged leukemia and a high level of DOT1L serves as the marker of poor prognosis in renal clear cell carcinoma and ovarian cancer cells." (PMID 39307938, 2024). "Despite this, targeting DOT1L remains a promising avenue for treating KMT2A rearranged leukemias, and novel small-molecule DOT1L inhibitors with improved PK profiles have already been identified." (PMID 37740239, 2023).
leukemia (continued). "From this perspective, prolonged inhibition of DOT1L seems to favor KMT2A-rearranged leukemia cells that completely lack PROM1/CD133 but do display LILRB4/CD85k and CD33 expression." (PMID 37740239, 2023). "As for Dot1l expression in disease condition, it was shown to potentially contribute to the development of multiple cancers including leukemia, breast cancer, ovarian cancer, prostate cancer, and other cancers." (PMID 37397258, 2023). "In agreement, treatment with small-molecule inhibitors of DOT1L also prevented the MLL-AF4-induced leukemia-like phenotype." (PMID 37720104, 2023). "Protein–protein interactions (PPI) between the most frequent MLL fusion partner proteins AF9/ENL and AF4 or histone methyltransferase DOT1L are drug targets for MLL-rearranged (MLL-r) leukemia." (PMID 37958457, 2023). "For this reason, DOT1L inhibitors were tested to treat MLL-r leukemia and antiestrogen-resistant breast cancer." (PMID 37620312, 2023). "We also found genetic depletion of gpp/DOT1L to rescue the leukemia-like phenotype of our MLL-r leukemia model." (PMID 37720104, 2023). "PPIs between AF9/ENL and AF4 or DOT1L are a potential drug target for MLL-r leukemia, as well as other cancers (e.g., AML) driven by SEC-mediated aberrant gene expression." (PMID 37958457, 2023). "Combinatorial inhibition of MOZ/MORF and DOT1L cooperatively induces differentiation of CALM-AF10-leukemia cells." (PMID 37031220, 2023). "Amongst them, Pinometostat, a first‐in‐class small‐molecule inhibitor targeting the H3K79 methyltransferase DOT1L has been used in a phase 1 clinical trial in MLL leukaemias." (PMID 37872885, 2023). "In mouse models, DOT1L has been studied as a potential therapeutic target in MLL-r leukemia, using inhibitors that either inhibit its catalytic activity or disrupt its interaction with MLL fusion partners." (PMID 37720104, 2023). "Knockdown or pharmacological inhibition of DOT1L was found to selectively inhibit MLL-r leukemia in cells, animal models and clinical trials." (PMID 37958457, 2023). "Scaffold protein menin, encoded by multiple endocrine neoplasia 1 gene (MEN1) and known to be involved in histone modification and epigenetic gene regulation, has been shown to physically bind DOT1L in leukaemia and breast cancer cells." (PMID 36333801, 2022). "For example, Mahmoudi and colleagues showed that, in cooperation with the leukemia-associated Mllt10/Af10, via H3K79 methylation DOT1L positively regulates the RNA elongation step during transcription of Wnt target genes." (PMID 35495127, 2022). "The multiple evidences provided for the efficacy of DOT1L inhibitors for both leukemia and solid tumors treatment were inducing a growth of interest in developing novel compounds with improved inhibitory potential and bioavailability." (PMID 35495127, 2022). "Correspondingly, DOT1L-mediated H3K79me2/3 was required to preserve accessibility and H3K27ac of intergenic enhancers in leukemia cell lines." (PMID 35733849, 2022). "Due to their own limitations in either potency or selectivity (e.g., compounds 8 h and 9e exhibit better anti-DOT1L activity but poor selectivity against MLL-rearranged leukemia cells than that of 3a and 3e), these compounds need further optimization." (PMID 35331314, 2022). "The MLL fusion protein recruits a histone methyl transferase (HMT), DOT1L, resulting in the aberrant methylation of MLL gene targets and enhanced expression of leukemia-associated genes." (PMID 35740427, 2022). "In this study, the authors tiled sgRNAs across DOT1L exonic regions, measuring the gene expression and barcodes in single mouse Mll::Af9 leukemia cells." (PMID 36497471, 2022). "We presented a general overview of therapeutic strategies against DOT1L for MLL-rearranged leukemias, including DOT1L enzymatic inhibitors, DOT1L degraders, PPI inhibitors, and combinatorial interventions." (PMID 35331314, 2022).